CDX2 (caudal type homeobox 2)
Diseases named in the same sentence as CDX2 in open-access papers (continued):
Sharing a sentence is not in itself a finding about the gene and the disease.
villous adenoma (3 papers, 2021 to 2025). An epithelial neoplasm morphologically characterized by the presence of a villous architectural pattern. "The epithelial tissue of the intestinal subtype resembles the villous adenoma of the colon and contains goblet cells, which express the MUC2 protein and the CDX2 transcription factor." (PMID 37575378, 2023). "Colonic villous adenoma-like growth pattern and immunohistochemical profile of MUC2-, MUC5AC- and CDX2-positivities but MUC1- and MUC6-negativities in the present case indicated that the lesion was consistent with the intestinal type IPMN." (PMID 34674710, 2021). "Some of the cells were morphologically similar to intestinal villous adenoma, but they were negative by CK20, SATB2, and CDX-2, so ectopic or tumor metastasis in the digestive mucosa was excluded." (PMID 40013097, 2025).
yolk sac tumor (3 papers, 2020 to 2024). A non-seminomatous malignant germ cell tumor composed of primitive germ cells. "ECs exhibiting intestinal-type features share morphological and phenotypical features with pure forms or somatic-type variants of yolk-sac tumors, in particular from those cases presenting endodermal-intestinal differentiation with glandular architecture and expression of CDX2 and CK20." (PMID 32781666, 2020). "Although not explored in our study, glandular yolk sac tumor is reported to be positive for CDX2, reflecting its endodermal differentiation; this can be a cause of misdiagnosis as metastatic gastrointestinal adenocarcinoma, especially in patients with a history of these malignancies." (PMID 34977100, 2021). "Tissues were also stained for CDX2, SOX2 and FOXA2, which were negative in accordance with the absence of yolk sac tumors (YST) and EC." (PMID 38097681, 2024).
acute leukemia (2 papers, 2020 to 2021). A clonal (malignant) hematopoietic disorder with an acute onset, affecting the bone marrow and the peripheral blood. "The intestine‐specific caudal‐related homeobox gene‐2 (CDX2) homeobox gene, while being a tumor suppressor in the gut, is ectopically expressed in a large proportion of acute leukemia and is associated with poor prognosis." (PMID 33960108, 2021). "In conclusion, this study shows that the ectopic expression of CDX2 in the hematopoietic lineage triggers acute leukemia associated with genome instability and profound changes in gene expression patterns." (PMID 33960108, 2021). "Cdx2-transgenic mice develop myelodysplastic syndrome with progression to acute leukemia associated with acquisition of additional driver mutations." (PMID 32541670, 2020). "Ectopic Cdx2 expression in HSPCs results in lethal MDS, characterized by abnormal blood cell counts, dysgranulopoiesis, and thrombocytopenia, followed by secondary transformation to acute leukemia (AL) in a percentage of surviving mice." (PMID 32541670, 2020).
appendiceal adenocarcinoma (2 papers, 2019). "CDX2 is typically expressed in a strong diffuse pattern in colorectal and appendiceal adenocarcinomas, with sensitivity of 100%, in contrast to their analogs in the upper GI and ovaries, where it is expressed focally." (PMID 31771640, 2019). "The appendiceal adenocarcinoma also showed positive immunoreaction for CK7, CK20, CDX-2, and SATB2 but was negative for estrogen receptor, progesterone receptor, Pax-8, CD56, synaptophysin, and chromogranin A." (PMID 31409389, 2019). "Both the appendiceal adenocarcinoma and malignant components of the OMT stained positive for CK7, CK20, CDX-2, and SATB2 but negative for estrogen receptor, progesterone receptor, and pax-8." (PMID 31409389, 2019).
asthma (2 papers, 2018 to 2023). "The logistic regression model adjusted for body mass index revealed that in the genotype model, carriers of the Cdx2 rs11568820-AA genotype were associated with a higher risk of developing asthma (p = 0.005; OR = 2.73; 95% CI = 1.36–5.67; AA vs. GG)." (PMID 36839181, 2023). "Although it is associated with the diagnosis of asthma, the CDX2 polymorphism hasbeen shown to have a protective effect in other studies." (PMID 30066819, 2018). "There was a positive association between homozygous CDX2 polymorphism,asthma and lower FEV1% values." (PMID 30066819, 2018). "In the evaluated sample, the promoter polymorphism, 4913G> A, known as CDX2, wasfrequent in the tested population (71.4%) and was positively associated with thediagnosis of asthma, when it was homozygous." (PMID 30066819, 2018). "CDX2 polymorphism was associated with the diagnosis of asthma, aswell as with lower FEV1% results in spirometry." (PMID 30066819, 2018). "This study provided information about the association between CDX2 polymorphism, andthe VD receptor gene promoter region, with the diagnosis of asthma, and lowerFEV1 values." (PMID 30066819, 2018). "However, the logistic regression analysis, where the effect described for the VDR Cdx2 (rs11568820) polymorphism on the risk of developing asthma was maintained, made it possible to avoid false positive associations." (PMID 36839181, 2023). "The Cdx2 (rs11568820) polymorphism was significantly associated with the susceptibility to asthma." (PMID 36839181, 2023). "The Cdx2 polymorphism was significantly associated with the susceptibility of asthma and could substantially act as a predictive biomarker of the disease." (PMID 36839181, 2023). "In line with our results is a study in a mixed pediatric population (n = 60 cases/17 controls, Brazil), which shows a significant association between the presence of the AA genotype in the VDR Cdx2 SNP and developing asthma (p = 0.003; AA vs. G)." (PMID 36839181, 2023). "The results of our study show a statistically significant association between the risk of asthma and the presence of the A allele in the VDR Cdx2 (rs11568820) polymorphism." (PMID 36839181, 2023). "Similarly to CDX2, it is possible that other polymorphisms or mutations inthe VD receptor gene, which are capable of modifying cellular interaction with thevitamin, are associated with the prevalence of asthma and, perhaps, with thedifficulty of controlling the disease." (PMID 30066819, 2018). "There are not yet any studies that positively correlate the Cdx2 polymorphism and asthma in an adult population, but it has been described in a pediatric population and in other respiratory conditions." (PMID 36839181, 2023). "CDX2 is capable of modifying cellinteraction between VDR and VD, and it could be associated with theprevalence of asthma, and the difficulty in controlling the disease." (PMID 30066819, 2018).
bladder tumor (2 papers, 2015 to 2022). "In addition to immunohistochemical CK7 and CK20 positivity, negative caudal-type homeobox 2 (CDX2) which is frequently expressed in tumors of gastrointestinal origin suggests primary bladder tumor." (PMID 26346068, 2015).
chronic atrophic gastritis (2 papers, 2020 to 2024). Atrophic gastritis that is persistent and long-standing. "The H-scores of HNF4α, CDX2, and KLF4 protein were 33.0 ± 7.6 vs. 122.1 ± 8.3 (P < 0.01), 17.0 ± 5.6 vs. 60.4 ± 5.9 (P < 0.01), and 58.8 ± 7.3 vs. 129.7 ± 6.5 (P < 0.01) in gastritis vs. IM tissues, respectively." (PMID 32655894, 2020). "To further confirm the relationship between TGR5 and metaplasia markers in IM, we detected TGR5, HNF4α, CDX2, and KLF4 expression using three consecutive slides of gastric tissue including 120 cases IM and 67 cases of chronic superficial gastritis by IHC." (PMID 32655894, 2020).
chronic gastritis (2 papers, 2019 to 2020). Inflammation of the stomach that is chronic in nature. "CDX2 could also be detected in chronic gastritis without evidence of metaplasia, suggesting that the onset of CDX2 expression preceded the metaplastic change." (PMID 31739541, 2019).
duodenal tumor (2 papers, 2017 to 2025). "The cancer cells in the duodenal tumor and lymph node both expressed the epithelial marker CDX2, as well as the neuroendocrine markers CD56, and synaptophysin, indicating that the metastasis originated from the duodenal tumor." (PMID 28881081, 2017). "Both pancreatic and duodenal tumors can express CDX2, but it may be weak or negative as well." (PMID 40553402, 2025).
endometriosis (2 papers, 2022 to 2025). The growth of functional endometrial tissue in anatomic sites outside the uterine body. "While these features are suggestive of endometriosis, immunohistochemical stains with a panel of CK7, ER, CK20, and CDX2 antibodies can be utilized to distinguish difficult cases of endometriosis." (PMID 40291266, 2025). "Immunohistological stains for the glands were focally positive for cytokeratin (CK) 7 and estrogen receptor (ER) and negative for CK20 and CDX2, which were consistent with endometriosis." (PMID 40291266, 2025). "WT1, CK20 and CDX2 were scarcely expressed and were not different between ovarian SMBT with and without endometriosis." (PMID 35387670, 2022).
gall bladder carcinomas (2 papers, 2017 to 2023). "CDX2 also stains over one-third (37.3%) of eCCAs and gall bladder carcinomas." (PMID 37174934, 2023).
gallbladder adenocarcinoma (2 papers, 2014 to 2021). A carcinoma that arises from glandular epithelial cells of the gall bladder. "CDX2 expression has been associated with prolonged survival in gastric, ovarian and gallbladder adenocarcinomas." (PMID 24489794, 2014).
gastric cardia carcinoma (2 papers, 2016 to 2019). A carcinoma that arises from epithelial cells of the cardia of stomach. "In gastric cardia cancer tissues, high expression of CDX2 is positively correlated with cell proliferation marker Ki6746." (PMID 30631044, 2019). "To investigate the relationship between CDX2, cell proliferation and H. pylori infection, we detected CDX2, Ki62 and H.pylori expression in 83 non-malignant gastric cardia mucosacases and 60 GCC specimens in the Chaoshan area, a high-risk region for esophageal and gastric cardia cancer." (PMID 27384681, 2016).
gastric disease (2 papers, 2017 to 2021). "And then we compared TCTP and CDX2 expressions of different gastric diseases in HpslyD positive." (PMID 28536478, 2017). "HpslyD positive H. pylori strain promotes the expression of CDX2 and TCTP with the development of gastric diseases." (PMID 28536478, 2017). "Our results show that HpSlyD induces CDX2 and VIL1 expression mediated through TCTP and contributes to IM and the development of gastric diseases." (PMID 28536478, 2017). "The IS of CDX2 and TCTP expressions are significantly higher in GC than that of IM-GA, which is also significantly higher in IM-GA than that of GS, indicating that the HpslyD positive H. pylori strain promotes the expression of CDX2 and TCTP with the development of gastric diseases." (PMID 28536478, 2017). "The expression of CDX2 and TCTP in gastric diseases was measured by immunohistochemistry." (PMID 28536478, 2017). "Similar to FABP1, the two-stage expression pattern of CDX2 and SOX9 during the initiation and development of GC was also reported previously, suggesting that these molecules might play different roles in different stages of gastric disease progression." (PMID 34957220, 2021).
gastric polyp (2 papers, 2014 to 2024). "Similarly, the previous pathology result of gastric polyp had tumor cells staining diffusely and strongly with CK7, Napsin, and TTF-1; patchy weak staining of CDX2; and negative for CK20." (PMID 39176211, 2024).
germ cell tumor (2 papers, 2012 to 2020). A benign or malignant, gonadal or extragonadal neoplasm that originates from germ cells. "CDX2, a transcription factor regulating early enterogenic differentiation and found to express in some testicular germ cell tumor, was also evaluated in this group of MMMTs." (PMID 22848863, 2012).
glioma (2 papers, 2021 to 2022). A benign or malignant brain and spinal cord tumor that arises from glial cells (astrocytes, oligodendrocytes, ependymal cells). "CDX2 promotes the malignant behavior of glioma cells; CDX2 knockdown suppresses glioma cell proliferation, migration and invasion and facilitates the apoptosis of glioma cells." (PMID 34440820, 2021). "In another study, lncRNA ZFAT-AS1, promotes the transcription of CDX2 (caudal type homeobox 2) by mediating histone H3 methylation on lysine 27 in a PRC2 dependent manner to facilitate the malignant biological behavior of glioma cells." (PMID 36009578, 2022).
H. pylori (2 papers, 2016 to 2023). "The cases with severe H. pylori infectionhadhigher CDX2 expression compared to cases with normal or mild H. pylori infection, suggesting a potential correlation with H. pylori infection and CDX2 expression in the gastric cardia cells." (PMID 27384681, 2016). "We have previously indicated the upregulation of CDX2 induced by H. pylori infection." (PMID 36959122, 2023).
imperforate anus (2 papers, 2022 to 2023). A congenital birth defect characterized by the absence of a normal anal opening. "We identified five patients with de novo or inherited pathogenic variants in CDX2 with clinical phenotypes that partially overlap with previous cases, that is, imperforate anus and renal, urogenital and limb abnormalities." (PMID 34671974, 2022).
Infertility (2 papers, 2019 to 2025). "Dasgupta and coworkers show that the Fok1 polymorphism is associated with infertility, while Cdx2 polymorphism was found to be associated with testosterone levels in PCOS." (PMID 31089932, 2019). "Furthermore, the results of our investigation revealed a significant correlation between the existence of the Cdx2 (rs11568820) polymorphism and an increased vulnerability to the development of PCOS and infertility." (PMID 39866289, 2025).
jejunal adenocarcinoma (2 papers, 2024 to 2026). A adenocarcinoma that involves the jejunum. "Histopathological analysis confirmed jejunal adenocarcinoma with positive CDX2 staining, ruling out other adenocarcinoma subtypes." (PMID 39434934, 2024). "Immunohistochemical analysis demonstrated CK7 positivity, CK20 positivity, CDX2 positivity, and PAX8 negativity in both ovarian and jejunal specimens, confirming a diagnosis of primary jejunal adenocarcinoma with ovarian metastasis." (PMID 42083706, 2026).
kidney tumor (2 papers, 2019 to 2024). "The kidney tumor of our patient, although the lack of immunoreactivity for CK-20 and CDX-2 ruled out the possibility of metastasis from intestinal origin, the negative results with TTF-1 and CK-7 was not supportive of pulmonary origin." (PMID 31484545, 2019). "Carcinomas from the urothelial tract and kidney tumors do not exhibit CDX2 expression." (PMID 39036214, 2024).
lung neoplasm (2 papers, 2014 to 2026). A benign or malignant, primary or metastatic neoplasm involving the lungs. "Negative staining for cytokeratin 7 (CK7), cytokeratin 20 (CK20), caudal-type homeobox transcription factor 2 (CDX2), and thyroid transcription factor 1 (TTF-1) helped exclude primary gastric, gastrointestinal, and pulmonary neoplasms." (PMID 41769517, 2026).
Lynch syndrome (2 papers, 2017 to 2018). An autosomal dominant hereditary neoplastic syndrome characterized by the development of colorectal carcinoma and a high risk of developing endometrial carcinoma, gastric carcinoma, ovarian carcinoma, renal pelvis carcinoma, and small intestinal carcinoma. "CDX2 status has been associated with mismatch repair dysfunction, a hallmark of hereditary CRC (e.g. Lynch syndrome), which is also observed in approximately 10% of sporadic primary CRC." (PMID 30602942, 2018). "We compared the expression patterns of cytokeratins (CK7 and CK20), mucins (MUC2/5 AC/6), CDX2 and β-catenin in Lynch syndrome and FCCTX." (PMID 28824332, 2017). "Expression of CDX2 was abundant without statistical significant differences between Lynch syndrome and FCCTX (93 and 99%, respectively)." (PMID 28824332, 2017).
neuroblastoma (2 papers, 2021 to 2023). Neuroblastoma (NB) is the most common solid, extracranial childhood tumor. "In addition, CDX2 was predicted to regulate MYCN, a transcription factor commonly amplified in aggressive neuroblastoma." (PMID 32940375, 2021).
pancreatic NEN (2 papers, 2023 to 2025). "Detailed characterization of pulmonary NEC, pulmonary carcinoid, pancreatic NEN, ileal NEN, and MiNEN was performed using immunohistochemical staining to detect pan-cytokeratin (panCK), Thyreoglobulin (TG), Calcitonin (CT) and the transcription factors CDX2, SATB2, TTF1, GATA3, ARX and PDX1." (PMID 41145514, 2025).
Peptic ulcer (2 papers, 2021 to 2023). The term peptic ulcer refers to acid peptic injury of the digestive tract, resulting in mucosal break reaching the submucosa. "In the UK Biobank, ABO, CDX2, CCKBRMUC1, MUC6, FUT2, PSCA, and GAST genes have been identified and found to be associated with peptic ulcer disease." (PMID 36678166, 2023).
tubular adenocarcinoma (2 papers, 2023). An infiltrating adenocarcinoma in which the malignant cells form tubular structures. "The pathological finding was well to moderately differentiated tubular adenocarcinoma, and immunohistochemistry showed that tumor cells were weakly positive for cytokeratin (CK) 7 and positive for CK20 and Caudal-type homeobox 2 (CDX2), consistent with liver metastases from sigmoid colon cancer." (PMID 37650976, 2023).
ZIKV infection (2 papers, 2019 to 2022). "Given that Cdx2 is essential for trophectoderm cell development, these data indicate that ZIKV infection interferes with trophectoderm fate." (PMID 35900100, 2022). "Consistent with our data demonstrating ZIKV infection of mouse trophectoderm, ZIKV E antigen was detected in CDX2+ human trophectoderm." (PMID 31519912, 2019).
acute lymphoblastic leukemia (1 paper, 2019). Leukemia with an acute onset, characterized by the presence of lymphoblasts in the bone marrow and the peripheral blood. "Up to 89% of AML cases, and up to 81% of acute lymphoblastic leukemia (ALL) cases, express CDX2 and at least for ALL, CDX2 expression levels were directly associated with the aggressiveness of the disease." (PMID 31739541, 2019).
acute monoblastic leukemia (1 paper, 2021). "Here, we report that turning on human CDX2 expression in the hematopoietic lineage of mice induces acute monoblastic leukemia, characterized by the decrease in erythroid and lymphoid cells at the benefit of immature monocytic and granulocytic cells." (PMID 33960108, 2021).
allergic rhinitis (1 paper, 2018). Inflammation of the nasal mucous membranes caused by an IgE-mediated response to external allergens. "Allergic rhinitis was present in 90% of asthmatics.Homozygous CDX2 was detected in 23% of the patients and absent in thecontrol group (p=0.03)." (PMID 30066819, 2018).
anemia (1 paper, 2020). A reduction in the number of red blood cells, the amount of hemoglobin, and/or the volume of packed red blood cells. "LysM:Cdx2 mice had significant neutrophil hypersegmentation compared with LysM-Cre controls, with leukocytosis, anemia, and splenomegaly, but unlike Scl:Cdx2 mice, did not exhibit thrombocytopenia and did not develop secondary AML." (PMID 32541670, 2020).
anorectal malformation (1 paper, 2022). "A causative role is further substantiated by the relationship between CDX2 and other proteins encoded by genes that were previously linked to caudal abnormalities in humans, for example, TBXT (sacral agenesis and other vertebral segmentation defects) and CDX1 (anorectal malformations)." (PMID 34671974, 2022).
Anxiety (1 paper, 2024). Intense feelings of nervousness, tension, or panic often arise in response to interpersonal stresses. "Furthermore, Cdx2-Cre;Grin2bfl/+ mice showed largely normal locomotor and anxiety-like behavior, except for a mild decrease in open-field locomotion." (PMID 38704508, 2024).